LRPPRC (leucine rich pentatricopeptide repeat containing)
Description:
May play a role in RNA metabolism in both nuclei and mitochondria. In the nucleus binds to HNRPA1-associated poly(A) mRNAs and is part of nmRNP complexes at late stages of mRNA maturation which are possibly associated with nuclear mRNA export. Positively modulates nuclear export of mRNAs containing the EIF4E sensitivity element (4ESE) by binding simultaneously to both EIF4E and the 4ESE and acting as a platform for assembly for the RNA export complex. Also binds to exportin XPO1/CRM1 to engage the nuclear pore and traffic the bound mRNAs to the cytoplasm. May bind mature mRNA in the nucleus outer membrane. In mitochondria binds to poly(A) mRNA. Plays a role in translation or stability of mitochondrially encoded cytochrome c oxidase (COX) subunits. May be involved in transcription regulation. Cooperates with PPARGC1A to regulate certain mitochondrially encoded genes and gluconeogenic genes and may regulate docking of PPARGC1A to transcription factors. Seems to be involved in the transcription regulation of the multidrug-related genes MDR1 and MVP. Part of a nuclear factor that binds to the invMED1 element of MDR1 and MVP gene promoters. Binds single-stranded DNA (By similarity). Required for maintaining mitochondrial potential. Suppresses the initiation of basal levels of autophagy and mitophagy by sustaining BCL2 levels.
Synonyms: LRP130; GP130; CLONE-23970; LSFC; MC4DN5
Tractability: Small molecule: a structure with a bound ligand is known. PROTAC: ubiquitination databases record sites on it; its protein half-life has been measured.
Gene: Protein-coding gene on chromosome 2 (43,886,224 to 43,996,226, reverse strand). Ensembl gene ENSG00000138095.
Subcellular location: Mitochondrion; Nucleus; Nucleus, nucleoplasm; Nucleus inner membrane; Nucleus outer membrane
Subcellular location (Human Protein Atlas): Mitochondria; Acrosome; End piece; Mid piece
Pathways (Reactome):
Metabolism of RNA: Mitochondrial RNA degradation; Mitochondrial mRNA modification
Gene Ontology:
Molecular function: actin filament binding; beta-tubulin binding; mRNA binding; protein binding; RNA binding; ubiquitin protein ligase binding; microtubule binding; mRNA 3'-UTR binding; single-stranded DNA binding
Biological process: mitochondrial mRNA polyadenylation; negative regulation of mitochondrial mRNA catabolic process; mitochondrion transport along microtubule; regulation of mitochondrial translation; negative regulation of mitochondrial RNA catabolic process; regulation of gene expression
Cellular component: condensed nuclear chromosome; cytoskeleton; membrane; microtubule; mitochondrial matrix; mitochondrial nucleoid; mitochondrion; nucleus; perinuclear region of cytoplasm; cytoplasm; nuclear inner membrane; nuclear outer membrane; nucleoplasm; ribonucleoprotein complex
Genetic constraint (gnomAD): Loss-of-function variants: 53 observed, 82.48 expected, observed/expected ratio (o/e) 0.64, 90% interval 0.51 to 0.81. The synonymous counts are far from expectation, so gnomAD's model fits this gene poorly and the ratio says little. Missense variants: 1,127 observed, 965.1 expected, observed/expected ratio (o/e) 1.17, 90% interval 1.11 to 1.23. Synonymous variants: 438 observed, 363.28 expected, observed/expected ratio (o/e) 1.21, 90% interval 1.11 to 1.3.
Gene-disease validity (ClinGen):
ClinGen rates the evidence that LRPPRC causes each of these diseases.
Leigh syndrome (autosomal recessive): Definitive. A progressive neurological disease defined by specific neuropathological features associating brainstem and basal ganglia lesions.
mitochondrial disease (autosomal recessive): Definitive.
Homologues: Orthologues: chimpanzee LRPPRC (99% identical), macaque LRPPRC (90% identical), rabbit LRPPRC (81% identical), pig LRPPRC (81% identical), dog LRPPRC (80% identical), rat Lrpprc (76% identical), mouse Lrpprc (75% identical), tropical clawed frog lrpprc (60% identical), zebrafish lrpprc (49% identical), Drosophila melanogaster bsf (28% identical), Drosophila melanogaster Lrpprc2 (16% identical).
Diseases named in the same sentence as LRPPRC in open-access papers:
LRPPRC is named in the same sentence as 104 diseases in open-access papers, as found by Europe PMC text mining. Sharing a sentence is not in itself a finding about the gene and the disease. The quoted sentences say what the papers report.
Leigh syndrome (46 papers, 2007 to 2026). "These include P27 dihydroxylation of Lrpprc (leucine-rich pentatricopeptide repeat containing), an RNA binding protein and transcriptional co-activator mutated in Leigh syndrome, a mitochondrial disease." (PMID 41638874, 2026). "Mutations in LRPPRC have been identified as a causative factor in Leigh syndrome, French-Canadian type (LSFC), a severe mitochondrial disorder characterized by neurodegeneration and impaired energy metabolism." (PMID 40885397, 2025). "LRPPRC, a known gene that causes Leigh syndrome, is a mitochondrial protein that binds with its protein partner SLIRP and keeps the transcriptome of the mitochondria steady." (PMID 38448908, 2024). "Its human ortholog LRPPRC (also known as Lrp130) plays a similar role, and mutations in the gene cause the French Canadian variant of Leigh syndrome, a neurodegenerative disorder." (PMID 39465903, 2024). "Mutations in LRPPRC can lead to Leigh syndrome, French-Canadian type (LSFC), a human disorder characterized by neurodegeneration and cytochrome c oxidase deficiency." (PMID 37496051, 2023). "Mutations in LRPPRC cause the early-onset progressive mitochondrial neurodegenerative disorder French-Canadian-type Leigh syndrome, characterized by defects in oxidative phosphorylation reminiscent to those found in prodromal PD." (PMID 35732154, 2022). "Mutations in the human homolog LRPPRC are implicated in a French–Canadian variant of Leigh syndrome." (PMID 33640490, 2021). "Mutations in leucine-rich pentatricopeptide repeat containing (LRPPRC), a protein involved in the maturation and stability of mitochondrial RNA, cause the French-Canadian variant of Leigh syndrome." (PMID 32635556, 2020). "LRPPRC mutations have been found to cause Leigh syndrome in a French–Canadian population and are associated with reduced levels of LRPPRC and lower steady-state levels of mitochondrial transcripts." (PMID 32733355, 2020). "In mice, LRPPRC knockout is embryonically lethal, and in humans, mutations in the LRPPRC gene underlie Leigh syndrome, French Canadian type." (PMID 31861673, 2019). "LRPPRC is a 130 kD protein that is defective in Leigh Syndrome French Canadian variant, a rare form of the mitochondrial disorder Leigh Syndrome." (PMID 25933096, 2015). "In a French Canadian population, mutations in human LRPPRC have been associated with Leigh Syndrome, an autosomal recessive neurodegenerative disorder with onset in infancy." (PMID 26176594, 2015). "A homozygous c.1061C>T, p.(Ala354Val) founder mutation in the LRPPRC gene underpins the founder French-Canadian variant of Leigh Syndrome (LSFC) identified in the Saguenay-Lac-Saint-Jean region of Québec." (PMID 26510951, 2015). "The PPR protein LRPPRC first came to attention when a mutation of the LRPPRC gene was shown to cause a rare French-Canadian variant of Leigh syndrome characterized by cytochrome c oxidase deficiency." (PMID 26247782, 2015). "The French-Canadian variant of COX-deficient Leigh syndrome is unique to the Saguenay-Lac-Saint-Jean region of Québec and is caused by a founder mutation in the LRPPRC gene." (PMID 26510951, 2015). "In particular, SURF1-deficient Leigh syndrome was found to have a more favorable survival outcome compared to Leigh syndrome associated with complex I-deficiency or LRPPRC mutations." (PMID 24731534, 2014). "LRPPRC is also implicated in the human disease known as Leigh syndrome, a French-Canadian type cytochrome c oxidase deficiency, which suggest an important role in mitochondrial metabolism." (PMID 22808186, 2012). "In fact, our laboratory used this approach to identify the gene LRPPRC, which encodes a critical regulator of mtRNA and when mutated is the underlying cause of a respiratory chain disorder called Leigh Syndrome French-Canadian variant." (PMID 19680543, 2009).
Leigh syndrome (continued). "LRPPRC is of central importance for OxPhos function, and patients harboring mutations in LRPPRC develop the French-Canadian variant of Leigh syndrome, a devastating hepatocerebral metabolic disorder." (PMID 19680543, 2009). "Hypergonadotropic hypogonadism has also been reported in patients with mitochondrial diseases, including mtDNA depletion syndromes (C10orf2, POLG variants), mitochondrial neurogastrointestinal encephalomyopathy (MNGIE), primary coenzyme Q10 deficiency, and Leigh syndrome caused by LRPPRC variants." (PMID 41480351, 2025). "Notably, mutations in the LRPPRC gene are conclusively linked to the development of Leigh syndrome (LSFC)." (PMID 41154608, 2025). "Given that mutations in LRPPRC result in Leigh syndrome, it is likely that Ben/Ubc13-PINK1-Park may regulate Mfn1 and Mfn2 in Leigh syndrome as well in other mitochondrial diseases." (PMID 37098042, 2023). "Loss of LRPPRC results in a neurometabolic disorder—French-Canadian Leigh Syndrome." (PMID 37098042, 2023). "Knockout of the leucine-rich pentatricopeptide repeat containing protein (LRPPRC)-encoding gene, whose mutations have been identified in Leigh syndrome, causes the defective assembly of the electron transport chain and triggers compensatory mitochondrial biogenesis." (PMID 36901848, 2023). "Mutations in LRPPRC are associated with the French-Canadian type of Leigh syndrome." (PMID 32962729, 2020). "Variants in the LRPPRC gene can produce the French-Canadian type of Leigh syndrome." (PMID 33426505, 2020). "Leigh Syndrome French Canadian variant, a rare form of Leigh Syndrome, is caused by mutations in the gene encoding leucine-rich pentatricopeptide repeat-containing protein (LRPPRC)." (PMID 27462273, 2016). "The inactivation of the LRPPRC gene, which has previously been associated with the neurodegenerative French Canadian Leigh Syndrome, results in a decrease in the production of mitochondria-encoded subunits of complex IV, thereby causing a reduction in complex IV activity." (PMID 26412102, 2015). "The human homolog of ppr is LRPPRC, a mitochondrial protein whose loss causes Leigh syndrome." (PMID 26176594, 2015). "Mutations in LRPPRC are responsible for the French Canadian variant of Leigh Syndrome (LSFC), a severe disorder characterized biochemically by a tissue-specific deficiency of cytochrome c oxidase (COX) and clinically by the occurrence of severe and deadly acidotic crises." (PMID 25835550, 2015). "The human LRPPRC gene encodes a leucine-rich pentatricopeptide repeat containing protein that is imported into mitochondria and that is mutated in patients with French Canadian Leigh Syndrome, a neurodegenerative disorder associated with complex IV deficiency." (PMID 26412102, 2015). "One of these mRNAs with an EPRS footprint overlapping with the start codon is LRPPRC (leucine-rich pentatricopeptide repeat containing), a nuclear-encoded mitochondrial protein key for mitochondrial translation and associated with the French Canadian Leigh syndrome (LSFC)." (PMID 38263329, 2024). "In contrast, UPRmt and mitochondrial hyperfusion may not protect against more drastic and long-term changes in mitochondrial proteostasis, such as in C. elegans in which mma-1 has been chronically inactivated or in French Canadian Leigh Syndrome patients carrying mutations in the LRPPRC gene." (PMID 26412102, 2015). "Several studies showed that LRPPRC is required for the efficient expression of the cytochrome c oxidase (COX) complex and its mutation underpins a rare French-Canadian variant of Leigh syndrome characterized by defective expression of COX51." (PMID 37563135, 2023). "Leigh syndrome, French-Canadian type (LSFC, MIM#220111) is a neurogenetic degenerative disorder caused by mutations in the nuclear gene leucine-rich pentatricopeptide repeat-containing (LRPPRC) localized on 2p16." (PMID 32972427, 2020).
Leigh syndrome (continued). "Leucine-rich PPR-motif-containing protein (LRPPRC), a member of the PPR family, is a known gene mutation that causes Leigh syndrome French-Canadian." (PMID 31178748, 2019). "The French-Canadian variant of COX-deficient Leigh syndrome (LSFC) is unique to Québec and caused by a founder mutation in the LRPPRC gene." (PMID 26510951, 2015). "The natural history of Leigh syndrome has been described for the subgroups of SURF1 deficiency, cytochrome c oxidase deficiency due to LRPPRC mutations and complex I deficiency." (PMID 24731534, 2014). "Another differentially regulated gene of particular interest in RC disease was LRPPRC, which is known to interact with FOXO1 and PGC-1alpha proteins and is mutated in French-Canadian Leigh syndrome with RC complex IV deficiency." (PMID 23894440, 2013). "In the first example, publicly available data was used to help identify LRPPRC as a specific gene involved in Leigh syndrome, a complex hereditary disease." (PMID 17319736, 2007). "The underlying mechanism involves LRPPRC mutations reducing mitochondrial mRNA levels, which compromises the proper assembly and function of cytochrome c oxidase (COX), ultimately leading to the pathogenesis of Leigh syndrome." (PMID 41154608, 2025).
hepatocellular carcinoma (12 papers, 2012 to 2025). A malignant tumor that arises from hepatocytes. "LRPPRC depletion synergistically enhances diethylnitrosamine-induced DNA damage, genome instability, and further tumorigenesis so that LRPPRC knockout mice develop more and larger hepatocellular carcinomas and have a shorter lifespan." (PMID 38779771, 2024). "LRPPRC suppresses genome instability and hepatocellular carcinomas and promotes survivals in mice by sustaining Yap-P27-mediated cell ploidy and P62-HDAC6-controlled autophagy maturation." (PMID 38779771, 2024). "LRPPRC is a newly discovered N6-methyladenosine (m6A) modification reader, which potentially affects hepatocellular carcinoma (HCC) progression." (PMID 37063837, 2023). "Among them, studies have shown that LRPPRC can promote G1/S conversion and cell proliferation in hepatocellular carcinoma." (PMID 37074800, 2023). "The anti-apoptotic effect of LRPPRC was enhanced by a significant decrease in cytochrome C oxidase activity in hepatocellular carcinoma cells with reduced expression of LRPPRC." (PMID 37399661, 2023). "LRPPRC enters the mitochondrial oxidative metabolism by delaying apoptosis of hepatocellular carcinoma cells." (PMID 37399661, 2023). "LRPPRC was discovered originally as a highly over-expressed transcript in human hepatocellular carcinoma (HepG2) cells, and has subsequently been described to have several diverse cellular functions." (PMID 22808186, 2012). "LRPPRC is an approximately 130 kDa protein that was first identified as over-expressed in the human liver carcinoma cell line HepG2." (PMID 22458888, 2012). "However, it has also been reported that LRPPRC protein levels are reduced in diethylnitrosamine-induced mouse hepatocellular carcinoma tissues, and the liver-specific deletion of Lrpprc in mice resulted in a higher likelihood of developing hepatocellular carcinoma and a shorter survival time." (PMID 38397966, 2024). "Previous studies showed that LRPPRC could negatively regulate mitochondrial antiviral signaling during hepatitis C virus infection and could suppress genome instability and hepatocellular carcinomas by sustaining Yap-P27-mediated cell ploidy and P62-HDAC6-mediated autophagy maturation." (PMID 35069534, 2021). "The tumor suppressive function of autophagy regulator MAP1S and its interactive protein LRPPRC has been documented in multiple types of cancers including human ovarian cancer, prostate cancer, gastric cancer and carcinogen-induced mouse hepatocellular carcinomas." (PMID 26571030, 2015). "PSMD14 also enhances hepatocellular carcinoma growth and metastasis by inhibiting GRB2 via deubiquitination and stabilizes LRPPRC via deubiquitination." (PMID 38643468, 2024). "In summary, this is a first study to analysis disulfidptosis-related genes in hepatocellular carcinoma, and we identified that SLC7A11 and LRPPRC could be used as independent prognostic factors for HCC." (PMID 37399661, 2023). "Analysis of human hepatocellular carcinoma (HCC) tissues revealed that SNHG17, LRPPRC, and c-Myc were significantly upregulated in HCC, and they showed a positive correlation with each other." (PMID 34671012, 2021).